TPR (translocated promoter region, nuclear basket protein)
Diseases named in the same sentence as TPR in open-access papers (continued):
Sharing a sentence is not in itself a finding about the gene and the disease.
bladder cancer (1 paper, 2022). "We obtained the results of immunohistochemical staining of PSMD14, PRPF19, PSMB5, and TPR in normal tissues and bladder cancer tissues and demonstrated that these four genes were highly expressed in tumor tissues and lowly expressed in normal tissues." (PMID 35898492, 2022).
Ewing sarcoma (1 paper, 2024). A small round cell tumor that lacks morphologic, immunohistochemical, and electron microscopic evidence of neuroectodermal differentiation. "The other two NTRK gene fusions in pediatrics were an LPP1::NTRK2 fusion (Ewing’s sarcoma), and a RAD51B::NTRK3 (PTC); we did not identify ETV6::NTRK3, TPR::NTRK1 – NTRK gene fusions were more commonly reported among pediatrics with solid tumors." (PMID 38967220, 2024).
glioblastoma (1 paper, 2017). The most malignant astrocytic tumor (WHO grade IV). "Another HOP peptide (anti-TPR), which inhibits the HOP-Hsp90 interaction, has been described to induce cell death in several cancer cell lines and produce a cytotoxic effect in glioblastomas, highlighting HOP as a potential target for GBM therapy." (PMID 28412969, 2017).
head and neck cancer (1 paper, 2024). A primary or metastatic malignant neoplasm affecting the head and neck. "We used this database to assess the dependence of a large panel of head and neck cancer cell lines on the expression of PLK1, AURKA, TPR, NUF2, NDC80, and TTK." (PMID 39392349, 2024).
HIV-1 infection (1 paper, 2018). The type species of lentivirus and the etiologic agent of acquired immunodeficiency syndrome (AIDS). "HIV-2 and SIVmac infection were inhibited by many Nup depletions and both were modestly sensitive to depletions of a number of Nups that did not affect HIV-1 infection (e.g. NUP155, TPR, NUP62, NUP54, NUPL1." (PMID 30084827, 2018).
Hutchinson-Gilford progeria syndrome (1 paper, 2022). "Most remarkably, progerin, a progeriatric isoform of Lamin A and causing the Hutchinson-Gilford progeria syndrome in humans, displaces Nup153 and TPR (the mammalian homologs of Nup60 and Mlp1/2) from the nuclear periphery." (PMID 35373738, 2022).
Obesity (1 paper, 2024). Accumulation of substantial excess body fat. "Taken together, our data suggest that an association exists between PBMC TPR and human obesity, and blocking TPR signaling attenuates the LPS- and/or FFA-induced inflammatory response in PBMCs." (PMID 39195211, 2024). "The objectives of this study are to assess the link between PBMC TPR and human obesity and determine the role and mechanisms by which TPR mediates the pro-inflammatory effects in human immune cells, in particular PBMCs." (PMID 39195211, 2024). "However, the role and mechanisms by which TPR mediates the pro-inflammatory effects of these obesity-related factors, in particular LPS and FFAs, in human immune cells are still unclear." (PMID 39195211, 2024). "Blocking TPR activity may be a therapeutic option to attenuate obesity-related inflammation and metabolic disorders." (PMID 39195211, 2024). "However, evidence for the link between PBMC TPR signaling and obesity in humans is still lacking." (PMID 39195211, 2024).
rhabdomyosarcoma (1 paper, 2015). A rare aggressive malignant mesenchymal neoplasm arising from skeletal muscle. "The salient finding of the present study is that constitutive activation of MET signaling by expression of TPR-MET oncogene induces rhabdomyosarcoma development by blocking myogenic differentiation and enhancing proliferation, migration and angiogenesis." (PMID 26384300, 2015). "To determine if activation of MET signaling pathways may be responsible for activation of oncogenic and metastatic pathways in rhabdomyosarcoma development, we transduced SMS-CTR cells using lentiviral vectors harboring TPR-MET oncogene." (PMID 26384300, 2015). "The effects of TPR-MET are also independent of myomiRs, miRNAs regulating myogenesis, which have previously been demonstrated to regulate rhabdomyosarcoma development." (PMID 26384300, 2015).
T-cell lymphomas (1 paper, 2009). "Similarly, transgenic mice carrying the TPR-MET gene (coding for an oncogenic TPR-MET fusion protein) develop Met-driven T-cell lymphomas." (PMID 19939254, 2009).
ZIKV infection (1 paper, 2020). "We found that while during DENV infection the integrity and distribution of at least three nucleoporins (Nup), Nup153, Nup98, and Nup62 were altered, during ZIKV infection, the integrity of TPR, Nup153, and Nup98 were modified." (PMID 32466480, 2020).
cancer (35 papers, 2006 to 2026). A tumor composed of atypical neoplastic, often pleomorphic cells that invade other tissues. "Lowly-connected interfacing proteins are no less interesting, as they include the HCV-binding protein SMURF2 and the cancer-mutated gene TPR, both of which have a connectivity of three." (PMID 24564909, 2013). "TPR is essential to a variety of nuclear functions such as the transport of mRNAs and proteins through nuclear pore, chromatin organization, and mitosis, whose mutations were detected in many kinds of cancers and contributed to cancer development and aging." (PMID 35898492, 2022). "Fusion of the 5′ end of the TPR gene with several different kinase genes is associated with cancer." (PMID 23110726, 2012). "Based on recent work on the TPr/TXA2 axis in cancer metastasis, it appears likely that the antimetastatic efficacy of ifetroban is also due at least in part to changes in tumor angiogenesis/endothelial function and immune modulation." (PMID 41233835, 2025). "Our data indicate that the prevention of tumor cell-platelet interactions via treatment with the TPr inhibitor ifetroban is effective at reducing cancer metastasis." (PMID 41233835, 2025). "Post-treatment cold tumors also acquired more cancer-specific mutations (i.e., BRCA2, TPR, OMD, RANBP2, EP300)." (PMID 38714665, 2024). "Of note, the TPR gene also had a highly significant codependency score but was driven by a single cancer type (kidney) and thus with less clear relevance to diverse tumor types." (PMID 37095494, 2023). "Together, all these observations suggest that the prevalent genetic alterations of TPR genes in cancer." (PMID 35614079, 2022). "Consistent with other cancers, PSMB5, TPR, and PRPF19 were independent prognostic risk factors in BCa, while PSMD14 seemed to be a protective factor, which was different from other types of cancers." (PMID 35898492, 2022). "The dysregulation of the ubiquitously transcribed TPR gene on the X chromosome (UTX) has been reported to be involved in the oncogenesis of several types of cancers." (PMID 29351209, 2018). "Antp-TPR has cytotoxic activity toward cancer cells through the decrease of Hsp90 client proteins in vitro and to induce effective antitumor activity in a xenograft model of human pancreatic cancer in mice in vivo." (PMID 25159299, 2014). "We previously reported that the newly designed Antp-TPR hybrid peptide targeting Hsp90 induced cytotoxic activity to cancer cells both in vitro and in vivo." (PMID 25159299, 2014). "In this study we found that the molecular activity of Antp-TPR is diverse from 17-AAG in its cancer-cell-killing mechanism." (PMID 22913813, 2012). "It was previously reported that 17-AAG induced the erUPR in rat histiocytoma, and in the current study we found that Antp-TPR has a different mechanism of action for cancer-cell killing compared with the conventional small-compound inhibitors targeting Hsp90." (PMID 22913813, 2012). "This suggests that, at least in human fibroblasts, ZC3HC1 may not play the structural role in establishing interconnections between TPR polypeptides at the nuclear basket which has been reported in cancer cells." (PMID 40443800, 2025). "This may be consistent with the chromosome segregation defects reported in human cancer cell lines upon TPR knockdown (Nakanoet al., 2010)." (PMID 40443800, 2025). "More recently, an appreciation that TPr could contribute to the spread of cancer via its multifaceted roles in the vasculature is developing." (PMID 41233835, 2025). "Silencing of TPR elicits a senescent-like phenotype in cancer cells." (PMID 39080077, 2024).
cancer (continued). "In addition, studies have reported that nuclear pore density increases in senescent cells, and nucleoporins such as TPR accumulate after treatment of HDAC inhibitors in the nucleus of cancer cells, resulting in the secretion of SASP." (PMID 37543653, 2023). "Therefore, we examined the mRNA level of TPR in the NCI-60 cancer cell lines from GSE5720 and GSE5846 with two independent datasets of genome-wide expression profiles using the Affymetrix HG-U133A array." (PMID 34793452, 2021). "In all fusion proteins, TPR N-terminal coiled-coil domain is maintained and fused to the partner kinase domain, resulting to allow dimerization that aberrantly activates kinases and drives the cancer progression." (PMID 34722501, 2021). "In addition to this Nup, we have demonstrated that TPR, a nuclear pore basket constituent present in cells at interphase, facilitates mitotic processes in cancer cells." (PMID 29568361, 2018). "Collectively, this study sheds light on a novel mitotic function of GSK3β in the regulation of TPR-dynein mediated centrosome homeostasis, which may facilitate the discovery of new treatment regimens for cancer targeting mitosis." (PMID 29568361, 2018). "Considering all of this background knowledge collectively, we hypothesize that GSK3β may sustain the mitotic process in cancer cells by interacting with critical mitotic mediators such as TPR and dynein sub-complexes." (PMID 29568361, 2018). "Furthermore, other interactions were found with proteins like HDAC1 and TPR which are known to be deregulated in several cancers." (PMID 25471943, 2014). "We next examined the rate of Antp-TPR-mediated cancer cell killing in the presence of R11-Hsp70." (PMID 25159299, 2014). "Our current data describe how Antp-TPR has the molecular features of a novel class of global Hsp90 inhibitor, which is capable of simultaneously disabling the multiple pools of client proteins to increase the erUPR in cancer cells." (PMID 22913813, 2012). "The rate of Antp-TPR hybrid peptide-mediated cancer-cell killing was further investigated." (PMID 22913813, 2012). "Thus, the complete pathway from aberrant expression of TPR to full disease may involve multiple cellular processes and vary in different cancer types." (PMID 34793452, 2021). "We herein explored whether the use of mesenchymal stromal cells (MSCs) engineered to exhibit altered proteasomal activity through de novo expression of the TPr complex can be exploited as a novel anti-cancer vaccine capable of triggering potent CD8 T-cell activation." (PMID 33542714, 2020). "Also, TPR regulates the nuclear export of unspliced RNA and participates in processing and degradation of aberrant mRNAs, a mechanism considered important for the regulation of genes and their deregulation in cancer cells." (PMID 31438847, 2019). "Antp-TPR elevated the ATP levels in cancer cells, which is coincident with the findings of our previous study involving flow cytometry analysis with annexin V staining, while treatment with Antp-TPR in the presence of R11-Hsp70 shifted the ATP dynamics compared with treatment with Antp-TPR alone." (PMID 25159299, 2014). "Thus, further study about the combination of Antp-TPR with other peptides or small compounds targeting Hsp70 may lead to significant improvements in the cytotoxic activity of Antp-TPR toward cancer cells." (PMID 25159299, 2014). "Antp-TPR might provide potent and selective therapeutic options for the treatment of cancer." (PMID 22913813, 2012). "Interestingly, since Antp-TPR peptide increased cytotoxic activity against cancer cells after induction of the erUPR it is expected that it might exert effective antitumor activity if it penetrates a tumor." (PMID 22913813, 2012). "We identified cancer genes recurrently overexpressed across the cohort, e.g., MDM4 in six and CDC73 and TPR in five tumors, respectively." (PMID 36230794, 2022). "Subsequent studies have reported fusions of TPR with kinases including TRK, FGFR1 and ALK in cancers." (PMID 34793452, 2021).
cancer (continued). "Firstly, EBC-1 and MKN-45 human cancer cells that harbor an amplified MET gene, and BaF3/TPR-Met cell that stably expressing a constitutively active oncogenic version TPR-MET were used." (PMID 27191264, 2016). "Finally, direct blockade of TXA2 synthase or TPr disrupts TXA2 signaling and reduces metastasis in experimental models of multiple cancer types." (PMID 41233835, 2025). "Immunohistochemical examination of primary tumors from 20 CRC patients showed higher expression of TPR in nuclei and nuclear membranes in cancer cells compared with non-neoplastic crypt cells." (PMID 29568361, 2018). "Antp-TPR with or without R11-Hsp70 did not increase the GSH concentration in cancer cells, whereas 17-AAG did." (PMID 25159299, 2014). "When we examined ATP dynamics in cancer cells after treatment with these peptides, single-cell level imaging with the LV200 system revealed that the treatment with Antp-TPR in the presence of R11-Hsp70 affected the dynamics, which was observed after treatment with Antp-TPR alone." (PMID 25159299, 2014). "Confocal laser scanning microscopy revealed penetration of the cancer cells by Antp-TPR and R11-Hsp70 labeled with TAMRA and FITC, respectively, in a time-dependent manner; this indicated the synergetic effect of Antp-TPR in a time-dependent manner." (PMID 25159299, 2014). "It was found that Antp-TPR with or without R11-Hsp70 decreased the GSH concentration in cancer cells." (PMID 25159299, 2014). "We also found that treatment with Antp-TPR, Hsp70-targeted peptide, or a combination of the two did not induce an increase in the glutathione concentrations in the cancer cells." (PMID 25159299, 2014). "We previously reported that novel Antp-TPR hybrid peptide, which can inhibit the interaction of Hsp90 with the TPR2A domain of Hop, induces selective cytotoxic activity to discriminate between normal and cancer cells both in vitro and in vivo." (PMID 22913813, 2012). "Among Cancer Gene Census genes, 1346 events were detected in 947 different loci, with the most recurrent ones being those in CLTCL1 (24 cases), CSMD3 (21 cases), MYH9 (20 cases), ANK1 (19 cases), TPR (19 cases), MYH11 (18 cases), PTPN13 (18 cases), and POLQ (17 cases)." (PMID 33809641, 2021). "It was also observed that the cytotoxic activity of both Antp-TPR alone and Antp-TPR in the presence of R11-Hsp70 toward normal mammary epithelial cells (MCF-10A) was less than that of these peptides against cancer cell lines, and that R11-Hsp70 did not affect the cytotoxic activity of 17-AAG." (PMID 25159299, 2014). "Furthermore, treatment with Antp-TPR in the presence of R11-Hsp70 did not induce up-regulation of Hsp90, Hsp70, Hsp27, or Hop proteins in these cancer cells." (PMID 25159299, 2014). "In addition, it was also found that the treatment of GB cells with Antp-TPR did not activate the Erk pathway, which is important for the differentiation and proliferation of cancer cells." (PMID 22913813, 2012). "However, the cytotoxic activity of Antp-TPR toward cancer cells was not affected in the presence of 2-phenylethynesulfonamide, which was recently introduced as a small-molecule inhibitor of Hsp70, although the cytotoxic activity of 17-AAG was increased under this condition." (PMID 25159299, 2014). "Since the Antp-TPR peptide did not increase the promoter activity of YME1L1 and GCP60 after induction of the mtUPR and Golgi stress, it is suggested that Antp-TPR might affect the erUPR specifically in cancer cells." (PMID 22913813, 2012).
tumor (22 papers, 2012 to 2026). "In these models, we demonstrated TPr inhibition, reduced platelet activation, reduced numbers of CTCs, and inhibition of tumor growth and metastasis to the lungs and liver." (PMID 41233835, 2025). "Co-treatment of platelets and tumor cells with ifetroban, as well as pre-treatment of platelets with ifetroban, both resulted in decreased tumor cell-platelet interactions compared to untreated cells and in the presence of the TPr agonist U46619." (PMID 41233835, 2025). "U46619 treatment increased the number of platelets adhering to tumor cells in culture, which was abrogated and even reduced compared to untreated cells in the presence of the TPr inhibitor, ifetroban." (PMID 41233835, 2025). "In each case, platelet-tumor cell adhesion was significantly increased when the TPr agonist U46619 was introduced, while pre-treatment with ifetroban (TPr antagonist), significantly reduced platelet-tumor cell adhesion." (PMID 41233835, 2025). "Platelet degranulation downstream of TPr is known to produce soluble mediators that contribute to tumor cell EMT, tumor angiogenesis and endothelial barrier function, and immune modulation." (PMID 41233835, 2025). "We chose the aggressive treatment regimen used here to determine that the TXA2/TPr pathway is critical for the initial adherence of platelets to CTCs and their survival within the vasculature events that can occur early upon tumor cell introduction." (PMID 41233835, 2025). "In sum, ifetroban retained its antimetastatic efficacy when tumor cells were injected directly in the bloodstream and when used to treat cell line-based tumors with TPr deleted from the tumor cell compartment." (PMID 41233835, 2025). "Blocking TPr with ifetroban was sufficient to prevent platelet activation and platelet-tumor cell adhesion in cellular co-cultures." (PMID 41233835, 2025). "Following clinical confirmation in the serum, we found that increased expression of these proteins, especially TPR and FGA, was associated with acquired resistance and tumor recurrence." (PMID 40722683, 2025). "In this study, we provided evidence that ifetroban reduces metastasis by inhibiting TPr signaling in platelets and interfering with the interaction of platelets and circulating tumor cells." (PMID 41233835, 2025). "Our method can not only uncover disease-causing genes with abnormal expression in tumor samples such as CD74, HGF, but it can also identify genes with stable expression yet crucial roles in LUSC, such as BRAF, KDM6A, MAP2K1, and TPR." (PMID 40136480, 2025). "The specific activation of the main signaling pathways (NFAT, NFkB, and AP1) after tumor recognition was measured using a triple reporter system in Jurkat cells (Jurkat-TPR)." (PMID 37795087, 2023). "Up-regulation of ROCK1 and TPR and down-regulation of ALDH4A1 and CLCA2 are positively associated with the processes of migration, metastasis, and invasion of tumor cells and negatively associated with proliferation." (PMID 31438847, 2019). "We next sought to establish the cell-type dependence of TPr inhibition on platelet-tumor cell adhesion with a series of treatment protocols that would activate/inhibit TPr selectively in platelets, tumor cells, or both in combination by using CD-61 as a measure of platelet activation." (PMID 41233835, 2025). "Moreover, we and others have shown that TPr disruption increases endothelial barrier function and prevents transendothelial migration of tumor cells in vitro." (PMID 41233835, 2025).